SPRED2 (sprouty related EVH1 domain containing 2)
Diseases named in the same sentence as SPRED2 in open-access papers (continued):
Sharing a sentence is not in itself a finding about the gene and the disease.
cancer (18 papers, 2015 to 2025). A tumor composed of atypical neoplastic, often pleomorphic cells that invade other tissues. "Therefore, oxLDL can significantly increase miR-210 expression, which causes SPRED2 downregulation leading to a high risk of both cancer and vascular diseases." (PMID 26254226, 2015). "Previous studies have demonstrated that SPRED2 expression is downregulated in several cancers, including prostate cancer, colorectal cancer, advanced urothelial carcinoma, hepatocellular carcinoma, lung adenocarcinoma, and BC." (PMID 41155378, 2025). "It has also been reported that endogenous SPRED2 suppresses cancer cell motility, epithelial–mesenchymal transition, and apoptosis, while regulating autophagy." (PMID 41155378, 2025). "Recent studies have underscored the pivotal role of SPRED2 in cancer development and progression, generating considerable research interests." (PMID 41155378, 2025). "Previously, we demonstrated that SPRED2 downregulates cancer cell properties by inhibiting the RAS/RAF/ERK pathway." (PMID 41155378, 2025). "Previous studies demonstrated the role of SPRED2 in the behaviors of cancer cells via the exogenous overexpression of this protein." (PMID 36902429, 2023). "We have been investigating the role of SPRED2 in inflammatory responses and cancer by analyzing human data and performing experiments using human cell lines and Spred2 KO mice." (PMID 36902429, 2023). "In conclusion, we have demonstrated new evidence that strongly suggests that endogenous SPRED2 plays a critical role in the suppression of cancer cell proliferation, EMT and stemness in HCC cells." (PMID 36902429, 2023). "This is the first study to suggest a functional role of endogenous SPRED2 in the regulation of cancer cell stemness." (PMID 36902429, 2023). "The levels of SPRED2 mRNA expression in cancer tissues were significantly lower than those in adjacent non-cancer tissues." (PMID 36902429, 2023). "By IHC, HCC cells were stained weakly for SPRED2, whereas adjacent non-cancer hepatocytes were moderately stained." (PMID 36902429, 2023). "Lower m6A levels in myeloid cells enhance cancer progression by blocking the YTHDF1-mediated translation of SPRED2, and knockout of METTL3 induced a higher count of M2 macrophages in the TME69." (PMID 35794212, 2022). "SPRED2 is involved in the development and progression of various cancer types, and its expression has been shown to be positively correlated with a better outcome of the disease." (PMID 35205702, 2022). "The miR1246 negatively regulated anti-oncogene Sprouty Related EVH1 Domain Containing 2 (SPRED2) which prevented cancer cell migration and invasion through Raf/MEK/ERK pathway." (PMID 33456561, 2021). "In urothelial tumors, we showed that membranous Spred2 protein was often detected in cancer categories, especially LGPUC and HGPUC." (PMID 34818323, 2021). "As an anti-oncogene, SPRED2 interacted with the Raf/MEK/ERK pathway to prevent cancer cell migration and invasion." (PMID 31492150, 2019). "AdSpred2 infection resulted in the formation of fewer colonies and more dead cells relative to the control virus, AdSpred2-ΔSPR and AdSpred2-AA, indicating a role of the LIR in Spred2-induced cancer cell death." (PMID 27028858, 2016). "Our present data suggest that reduced SPRED2 expression in cancer may contribute to cancer proliferation and progression, at least in part, by inhibiting autophagic activities." (PMID 38892460, 2024). "We and others have shown that SPRED2 expression is downregulated in many cancers, including HCC." (PMID 38892460, 2024). "The downregulation of SPRED2 expression was detected in advanced human cancers, including HCC." (PMID 36902429, 2023). "Moreover, pharmacological inhibition of autophagy and knockdown of the key autophagy-related genes decreases Spred2-induced cancer cell death, indicating that Spred2 triggers cancer cell death in an autophagy-dependent manner." (PMID 27028858, 2016).
cancer (continued). "Furthermore, our data provide more information to explain how miR-210 expression is regulated and how miR-210 affects SPRED2 to influence cancer prognoses and vascular diseases." (PMID 26254226, 2015). "Thus, maintaining the endogenous SPRED2 level in malignant cells could be a novel treatment strategy in order to inhibit not only cancer cell growth and progression, but also the acquisition of EMT and stemness." (PMID 36902429, 2023). "Spred2 may downregulate cancer cell proliferation through an ERK-MAPK independent pathway in IUC." (PMID 34818323, 2021). "SPRED2 mRNA expression levels were also analyzed in 40 pairs of HCC and adjacent non-cancer tissues collected at the Okayama University Hospital by RT-qPCR." (PMID 36902429, 2023). "SPRED2, an inhibitor of the MAPK signal transduction pathway, has been found to be downregulated in various cancers." (PMID 35205702, 2022). "Hypo-methylated gDMs like MX2, OAS2, SPRED2, ADAP1, and SLC17A9 genes showed significant increased expression in cancer stage IV compared to stage I." (PMID 36329447, 2022). "Up-regulated expressions of the hypo-methylated gDMs in cancer were observed for OAS2, MX2, APOL3, ABHD8, RASSF1, SIGIRR, and SPRED2." (PMID 36329447, 2022). "METTL3-mediated m6A modification and upregulation of miR-1246 thus negatively regulate SPRED2 and inactivate MAPK pathway to promote cancer metastasis." (PMID 33814008, 2021). "Suppression of SPRED2 inhibits the phosphorylation of RAF/MEK/ERK proteins and abolishes its suppressive effect on migration and invasive capacity of cancer cells." (PMID 33814008, 2021). "Our screening procedure was robust as a subset of the highly ranked genes (BAX, BIM, BAP1, and SPRED2) had previously been correlated to either CML progression, imatinib resistance, or resistance to alternative therapies in different cancer types." (PMID 38831555, 2020). "Our data suggested that oxLDL-induced miR-210 can enhance SPRED2/ERK/c-Fos/MMP signaling, which explains oxLDL/miR-210′s effect on the three types of cancers tested in the present study." (PMID 26254226, 2015). "It is possible that downregulated endogenous SPRED2 in cancer, including HCC, may play a role in the regulation of cancer stem cells (CSCs)." (PMID 36902429, 2023). "The downregulation of SPRED2, a negative regulator of the ERK1/2 pathway, was previously detected in human cancers; however, the biological consequence remains unknown." (PMID 36902429, 2023). "Increased Spred2 expression may affect the activation of the Ras/Raf/ERK-MAPK pathway and subsequent cancer growth." (PMID 34818323, 2021). "We next compared the correlation between pERK score/Ki67 index and membranous Spred2 expression (negative: M-, positive: M+) in cancer categories." (PMID 34818323, 2021). "SPRED2 was the downstream target of miR-1246, and downregulation of SPRED2 could reverse the inhibition of MAPK pathway, thus promoting cancer metastasis and stemness." (PMID 34345203, 2021). "Since Spred2 inhibits the ERK pathway and subsequent cell proliferation, we compared the relationship between membranous Spred2 protein expression and pERK score/Ki67 index in each cancer category." (PMID 34818323, 2021). "To explore potential involvements of NF and SPRED2 in the phenotypes of BC cells, we first analyzed the expression of NF1 and SPRED2 mRNA in 57 human BC cell lines representing different subtypes using raw read count data from the Cancer Cell Line Encyclopedia." (PMID 41155378, 2025). "Sprouty-related enabled/vasodilator-stimulated phosphoprotein homology 1 domain containing 2 (SPRED2) is an inhibitor of the mitogen-activated protein kinase (MAPK)/extracellular signal-regulated kinase (ERK) pathway and has been shown to promote autophagy in several cancers." (PMID 38892460, 2024).
cancer (continued). "Thus, our pathological findings suggest that Spred2 counters cancer progression in non-invasive papillary carcinoma possibly through inhibiting the Ras/Raf/ERK-MAPK pathway, but this regulatory mechanism is lost in cancers with high malignancy." (PMID 34818323, 2021). "Thus, there was a negative correlation between SPRED2 levels and cancer grades." (PMID 36902429, 2023). "Although pERK score was not different between Spred2 M- and Spred2 M+ in IUC, Ki67 index was decreased in Spred2 M+ as compared to Spred2 M-, suggesting that Spred2 may downregulate cancer cell proliferation through a mechanism independent of ERK-MAPK in IUC." (PMID 34818323, 2021).
infection (3 papers, 2015 to 2025). The state of being infected such as from the introduction of a foreign agent such as serum, vaccine, antigenic substance or organism. "The most significant longitudinal changes in PBMC DNAme throughout infection were at the CpG sites associated with the SPRED2 (hypomethylation) and ZBTB7B, also known as ThPOK (hypermethylation) genes." (PMID 40662355, 2025). "Relative to control virus, Ad-Spred2 infection increased the fraction of cells staining with Annexin V and PI at 24, 48 and 72 h, suggesting that Spred2 may induce apoptosis in these cells." (PMID 27028858, 2016). "However, Spred2 interference had little effect on the expression of transcription factor PU.1, which supports myeloid cell lineage differentiation, at day 3 post-infection." (PMID 25688862, 2015).
SPRED2 also shares sentences with these, for which no sentence is quoted: chronic myelogenous leukemia (2 papers); obsessive-compulsive disorder (2); bacterial infections (1); cardiovascular disease (1); cervical carcinoma (1); genetic disorder (1); Glucose intolerance (1); hyperaldosteronism (1); Hyperglycemia (1); infiltrating urothelial carcinoma (1); inflammation (1); Legius syndrome (1); leukemia (1); liver diseases (1); non-alcoholic steatohepatitis (1); peritonitis (1); prostatic adenocarcinoma (1); psoriasis (1); pulmonary fibrosis (1); systemic lupus erythematosus (1); ulcerative colitis (1).